GZMB (granzyme B)
Diseases named in the same sentence as GZMB in open-access papers (continued):
Sharing a sentence is not in itself a finding about the gene and the disease.
tumor (continued). "Granzyme B is known to be delivered by perforin into target tumor cells, where it induces apoptosis by cleaving critical substrates." (PMID 25009582, 2014). "The cytotoxic granules Perforin and Granzyme-B cooperatively combine to form a complex which is released into the cytoplasm of infected cells and tumor cells." (PMID 25274283, 2014). "Granzyme B is an important mechanism used by NK cells to induce the death of the target cells and it plays a crucial role in the control of tumor growth in vivo." (PMID 24919191, 2014). "As shown by our research group and others, perforin and/or granzyme B-producing DC are also capable of killing tumour cells, which favour the idea that the increased killing of CaSki tumour cells occurs via a perforin/granzyme B-dependent mechanism." (PMID 24979331, 2014). "Our data showed that adoptive transfer of STZ-diabetic CD8+ effector cells resulted in fewer tumor-infiltrating T cells as well as less production of perforin, Granzyme B and TNFα in situ." (PMID 25390652, 2014). "The tumor cells revealed a positive immunoreaction for cluster of differentiation (CD)3ɛ, CD56, Epstein-Barr virus (EBV)-encoded small RNAs, granzyme B and TIA1, with a Ki67 of 60–70%." (PMID 25289105, 2014). "In a recent study, we screened the tumor microenvironment of various tumors for a novel regulatory B cell subset characterized by unique expression of the serine protease granzyme B (GrB) and potent GrBdependent T cell-suppressive activity." (PMID 25594063, 2014). "Cells isolated from the tumor of mice treated with either CpG ODN or 3M-052 had higher levels of expression of IL-12, IFNγ and granzyme B than tumor infiltrating cells from untreated mice (p <.05)." (PMID 24982761, 2014). "Since Granzyme B is an important marker of activated cytotoxic T-lymphocytes and a prerequisite for the lysing of tumour cells, Granzyme B secretion assays were carried out to confirm this." (PMID 24885328, 2014). "As expected, the cytotoxic molecule GzmB was also produced by CD8+CD43+ T cells after tumor challenge." (PMID 22890822, 2013). "We therefore analyzed the impact of arginine deficiency on secretion of IFN-γ/granzyme B/perforin and the cytotoxic capacity of T cells in the MART-1 tumor antigen specific model." (PMID 23717444, 2013). "This, together with the effect of cytotoxic molecules, including perforin, granzyme B and TIA-1 released by the malignant NK cells, and together with the tumour-associated inflammatory process, cause the widespread tissue damage and necrosis." (PMID 23327615, 2013). "To this end, we performed kinetic analysis of cytokine and granzyme B (GzmB) expression in T cells after tumor challenge." (PMID 22890822, 2013). "When NK cells are activated by MIC A/B, which are ligands for the activating receptor NKG2D on the tumor surface, perforin and granzyme B are released to the tumor cell, resulting in mediation of apoptosis." (PMID 23940545, 2013). "IL-12p70, which strongly promotes the differentiation of type-1 T-cells, enhances IFNγ and granzyme B production, prolongs T-cell survival and enhances immune recognition of tumor antigen-expressing cells." (PMID 26344346, 2013). "CTLs utilize a number of mechanisms to kill tumour cells including release of cytolytic granules containing perforin and granzyme B, as well as the expression of the death receptor ligand FasL that interact with the Fas receptors on target cells, respectively." (PMID 23922331, 2013). "Remarkably, tumor-induced activation of Foxp3− CD4+ T cells in drLN also resulted in their differentiation into GzmB-producing cells, suggesting a potential cytotoxic role for these cells." (PMID 22890822, 2013). "In contrast, miR-27a* is able to negatively regulate NK cell cytotoxicity by silencing the genes PRF1 and GZMB, as shown by the knockdown of miR-27a* in NK cells, which leads to decreased tumour growth in a human tumour xenograft model." (PMID 23478435, 2013).
tumor (continued). "Granzyme B (grB) derived from E. coli has been shown to induce apoptosis in tumor target cells via perforin pores that trigger the release of endocytosed grB." (PMID 22829941, 2012). "Granzyme B selectively reduced the proportion of membrane Hsp70-positive cells in CT26 tumor spheroids." (PMID 22829941, 2012). "The reduction of tumor growth was associated with higher TNF-α and granzyme B production, which are both known to induce programmed cell death." (PMID 23028986, 2012). "Binding of NK cells to this epitope results in GzmB-mediated but perforin-independent apoptosis of tumor target cells." (PMID 22438997, 2012). "With high expression of granzyme B and perforin, we expected NK cells expanded with mbIL21 to be cytotoxic against tumor targets." (PMID 22279576, 2012). "Considering that activated NK cells kill Hsp70 membrane positive tumor cells by GzmB-mediated apoptosis and having observed up-regulation of GzmB protein expression, we assessed the effect of parasitized erythrocytes on GzmB release of NK cells." (PMID 22438997, 2012). "Still, the ratio of CD8+Granzyme B+ cells to CD4+CD25hi Treg cells was higher in the unaffected then the tumor mucosa." (PMID 22319577, 2012). "Still, the ratio of CD8+Granzyme B+ cells to CD4+CD25hi Treg cells was significantly higher (p<0.01) in the unaffected then the tumor mucosa." (PMID 22319577, 2012). "In parallel, frequencies of activated CD4+ conventional T cells with a Th1 profile were decreased in the tumor, while granzyme B+ putative cytotoxic CD8+ cells were present." (PMID 22319577, 2012). "Recently it was shown that Hsp70 recognition by NK cells leads to apoptosis of tumor cells in a GzmB-dependent but perforin-independent manner." (PMID 22438997, 2012). "We have previously reported that human recombinant granzyme B (grB) mediates apoptosis in membrane heat shock protein 70 (Hsp70)-positive tumor cells in a perforin-independent manner." (PMID 22829941, 2012). "It has been shown that doxorubicin, cisplatin, and paclitaxel can sensitize tumor cells to the cytolytic effect of CD8+ T cells by making them permeable to granzyme B via mannose-6-phosphate receptors on the surface of tumor cells." (PMID 22400040, 2012). "Although cytotoxic CD4+ and CD8+ T cells appear to mediate tumor killing using the same effector molecules, such as granzyme B and perforin, they target MHC-II and MHC-I-restricted antigens, respectively." (PMID 22400040, 2012). "Using our tumor mouse model with LLC-MUC1 cells, we assessed the tumor-specific (MUC1 versus irrelevant OVA) production of IFN-γ and granzyme B in TdLN cells by enzyme-linked immunospot (ELISPOT) assay." (PMID 21931708, 2011). "By releasing various cytokines, such as perforin and granzyme B, these effector T cells are capable of inducing apoptotic death of tumor cells." (PMID 22190971, 2011). "We have previously shown that TKD/IL-2-activated NK cells kill their tumor target cells via a perforin-independent, granzyme B mediated lysis." (PMID 21179573, 2010). "Given the importance of the TSLN in tumor response, this additional increase in granzyme B production indicates that improved cytolytic activity can be facilitated by the addition of RU486 treatment to the Ad5IL-12 vector." (PMID 20946663, 2010). "The addition of RU486 to Ad5IL-12 vector therapy enhanced tumor cytotoxicity as measured by granzyme B production against TRAMP-C1 tumor targets from isolated TSLN lymphocytes." (PMID 20946663, 2010). "These perforin and granzyme B expressing cytotoxic T lymphocytes were highly cytolytic towards tumor cells in vitro." (PMID 20976143, 2010). "Granzyme B is an important effector molecule of cell-mediated immunity correlating to effective tumor immune response and measurement of its levels correlate well to total cellular cytotoxicity." (PMID 20946663, 2010).
tumor (continued). "This is consistent with the fact that lymphocytes can kill foreign or tumor cells by other cytotoxic mechanisms, such as release of granzyme B or perforin." (PMID 19698142, 2009). "Our data showed that IL-2 signal at priming stage in vitro drove development of CD8+ effector cells which produced greater quantities of IFNγ and Granzyme B when encountered the tumor in vivo." (PMID 19901991, 2009). "Murine studies indicate that granzyme B is involved in the Treg-mediated suppression of anti-tumor immunity in the tumor microenvironment and in the Treg-mediated maintenance of allograft survival." (PMID 19930596, 2009). "Recent data in the mouse has reported the important role of granzyme B in the suppression of immune system against tumor." (PMID 20169125, 2009). "In the tumor microenvironment, granzyme B is important for Treg-mediated suppression of tumor clearance." (PMID 19930596, 2009). "Similar to the results for MHC class I, the expression of MHC class II in tumor epithelium was positively associated with various T cell markers, including CD3, CD4, CD8, CD45RO, TIA-1, Granzyme B, CD25 and FoxP3." (PMID 19641607, 2009). "The results showed that there were more Granzyme B- and IFNγ- producing cells in the tumor in mice receiving P14IL-2 (0 h) than other groups." (PMID 19901991, 2009). "The perforin/granzyme-B system is an important mechanism of CTL-mediated tumour cell destruction and also contributes to NKT-cell cytotoxicity against U937 cells." (PMID 17311012, 2007). "This was particularly evident for NK (CD56 and NK1) and cytotoxic markers (Granzyme B and TiA1) inside residual tumour aggregates." (PMID 16404427, 2006). "Natural killer and cytotoxic cells (TiA1 or Granzyme B) tended to be more numerous in contact with residual tumour cells in the TAXHER01 tumours, with significant differences demonstrated for TiA1 (P<0.05) and NK1 staining (P<0.01)." (PMID 16404427, 2006). "The presence of increased numbers of NK cells in tumour infiltrates after trastuzumab treatment, as well as the presence of cytotoxic proteins such as Granzyme B, lends support to a role for NK cells in trastuzumab-induced tumour regression." (PMID 16404427, 2006). "These activated cells induced apoptosis in ESb-MP tumour cells via released perforin and granzyme B." (PMID 11875749, 2002). "The lysis of ESb-MP tumour cells was almost completely inhibited by the perforin (concanamycin A) and granzyme B inhibitors." (PMID 11875749, 2002). "Granzyme B and perforin-producing cells, which mediate cytotoxic killing of tumor cells, were significantly increased in all groups transfected with ssRNAs expressing co-stimulatory molecules, with the ssRNA-OX40L-transfected group showing the highest increase." (PMID 41541266, 2026). "Moreover, the impaired secretion of cytotoxic molecules (IFN‐γ and Granzyme B) by activated CD4+ T cells was reversed by TGF‐β antibody treatment in HBx‐overexpressing tumours." (PMID 41492119, 2026). "Blocking the hydrolytic shedding of MICB may have promoted the secretion of perforin and granzyme B, leading to more NK cell infiltration of the tumor, which correlates with the activation of immune anti-tumor by MICB binding to ligand NKG2D." (PMID 41516373, 2026). "Moreover, CD47 blockade in effector T cells increases granzyme B expression, further augmenting Cytotoxic T lymphocytes mediated tumor killing." (PMID 40926176, 2026). "Notably, granzyme B and IFN-γ expression in CD8+ and NK cells were strongly associated with tumor growth inhibition." (PMID 41424839, 2026). "Similarly, proliferating cytotoxic T cells were associated with favorable prognosis, as well as localization near tumor cells and high expression of key cytotoxic molecules such as GZMB." (PMID 41201451, 2026).
tumor (continued). "In a mouse xenograft model of lung cancer, the combination of PD-L1 blockade and Gal-3 inhibitor synergistically reduced tumor growth, which was accompanied by increased infiltration of CD3+ tumor-infiltrating lymphocytes (TILs) and granzyme B release into tumors." (PMID 40566589, 2025). "In summary, GZMB displays a paradoxical role in tumor initiation and progression." (PMID 41567188, 2025). "Thus, the use of combined granzyme B/TSC treatment resulted in an increase in the intensity of tumor growth inhibition compared to treatment with either drug alone." (PMID 40766321, 2025). "Additionally, CTLs secreted perforin and GzmB, which led to an enhancement in the anti-tumor immune response." (PMID 40698137, 2025). "Additionally, ILC3s produce factors that can directly inhibit tumor growth or induce apoptosis in cancer cells, such as Granzyme B and IFN-γ." (PMID 40497988, 2025). "Granzyme B plays a dual role in this environment: it can act to promote tumor control by killing tumor cells, but it can also contribute to tumor escape from the immune system through immunosuppressive effects mediated by various immune cells present in the TME." (PMID 40766321, 2025). "CD8 + T cells can recognize and eliminate tumor cells through perforin and granzyme B pathways." (PMID 40441260, 2025). "GZMB mediated cleavage of its substrates in extracellular matrix such as decorin, fibronectin, vitronectin might facilitate tumor survival signaling and metastasis." (PMID 40236693, 2025). "These modified T cells can directly bind to specific antigens on tumor cell surfaces and become activated, killing tumor cells by releasing perforin, granzyme B, and other cytokines, and recruiting endogenous immune cells for further tumor cell destruction, thereby achieving therapeutic goals." (PMID 40469307, 2025). "Tumor-derived lactate and the accompanying microenvironment acidification are known to inhibit NK cell effector functions (e.g., the release of perforin, granzyme B, and IFN-γ), downregulate activating receptor expression, and impair cytotoxicity against tumor cells." (PMID 41463052, 2025). "Additionally, qRT-PCR analysis revealed that the mRNA expression levels of IFN-γ, Granzyme B, Perforin, and CD107a were significantly higher in the tumor tissues of EPE-treated mice than in the untreated group." (PMID 41357886, 2025). "Additionally, the vaccine enhanced T‐cell and macrophage infiltration into the tumor microenvironment, accompanied by increased granzyme B levels, which likely contributed to its potent antitumor effects." (PMID 40729737, 2025). "In the future, the treatment of many diseases may benefit from the successful application of granzyme B imaging to tumours." (PMID 39747850, 2025). "Prior studies using L‐lactate concentrations (e.g., 40 mM) showed enhanced tumor infiltration, granzyme B and interferon‐γ in activated CD8+ T‐cells, demonstrating that lactate is a critical regulator of T‐cell function and signaling pathways in response to physiological stressors such as exercise." (PMID 40705846, 2025). "Importantly, co-expression of both perforin and granzyme B was found to dramatically reduce Hep-2 cancer cell proliferation, indicating a synergistic effect of these two key cytotoxic effectors in inhibiting tumor growth." (PMID 40766321, 2025). "To study that whether GB2 could prevent T cell dysfunction, we evaluated effector molecules IFN-γ and GZMB in tumor, serum, and tumor draining lymph nodes (TDLN)." (PMID 39744236, 2025). "Cytotoxic ILC1, with the ability to produce granzyme B, increased in the tumor site." (PMID 39877637, 2025). "Meanwhile, CD8+ T cells can induce tumor cell apoptosis by releasing granzyme B." (PMID 41007849, 2025). "Additionally, the T‐cell cytotoxic anti‐tumor effector molecule Granzyme B (GZMB) was among the top‐ranked and up‐regulated genes in GATA3‐low tumors." (PMID 41024411, 2025).
tumor (continued). "Finally, IFN-responsive cancer cells, C1q macrophages, and activated GzmB+ Tc gradually increase as the tumor progresses." (PMID 41280683, 2025). "BC patients who experienced positive clinical outcomes demonstrated a greater infiltration of cytotoxic CD8+ T cells that were positive for granzyme B. This finding suggests a more robust and active immune response within the tumor microenvironment of these patients." (PMID 40287406, 2025). "We classified the IHC staining slides and counted the CD3+ and Granzyme B+ cells in the tumor area." (PMID 40612678, 2025). "This discovery points towards a novel research direction where both GZMB and PI-9 inhibitors could be precisely targeted to tumor cells." (PMID 41567188, 2025). "In addition, the cleavage of caspase-3-related sites by GzmB can activate the GSDME protein as a tumor suppressor." (PMID 40698137, 2025). "Furthermore, the combination therapy group showed a further increase in the infiltration of CD8+ T cells and the expression of Granzyme B in the tumor tissue compared to the monotherapy groups." (PMID 40430847, 2025). "Detection of killer cytokines IFNG/IFN-γ, TNF/TNF-α, and GZMB secreted by CD8+ T cells revealed that reduced circGRAMD4 expression relieved tumor cell-induced immunosuppression, whereas increased circGRAMD4 expression suppressed the production or release of these immune factors." (PMID 40373256, 2025). "GZMB also plays a role in regulating the EMT in tumor cells." (PMID 41567188, 2025). "Moreover, PDL2 EVs led to a significant reduction in tumour‐infiltrating granzyme B+ CD8 T cells compared to shPDL2 EVs." (PMID 40135876, 2025). "However, recent evidence increasingly demonstrates that GZMB also exerts immunosuppressive effects within the tumor microenvironment." (PMID 41567188, 2025). "Combining VISTA inhibitors with anti–CTLA-4 or anti–PD-1 antibodies overcomes adaptive resistance mechanisms and leads to robust tumor regression in murine melanoma models by reducing Treg frequencies and increasing granzyme B+ cytotoxic T lymphocytes in the tumor." (PMID 40821795, 2025). "Furthermore, H-151 not only inhibited the p-STING/p-IRF3 axis but also significantly reduced the expression of T cell infiltration and activation markers (CD3D and CD69) as well as anti-tumor factors (GZMB, IFNγ, and TNFα)." (PMID 40846839, 2025). "In parallel, research has demonstrated that certain tumor cells also express GZMB." (PMID 41567188, 2025). "Similarly, the expression levels of CD25, CD69, and effector molecules IFNγ and GZMB were significantly increased in T cells co‐cultured with I3A‐treated B16‐OVA tumor cells." (PMID 40583248, 2025). "Our in vitro and in vivo results demonstrated that DS promotes DC maturation and enhances the secretion of effector molecules (IFN-γ/GzmB) by tumor-infiltrating CD8+ T cells, establishing the role of DS in orchestrating DC-CD8+ T-cell immunity for tumor suppression." (PMID 40625660, 2025). "Moreover, human granzyme B staining of tumor tissue revealed positive cells in all the treated groups, confirming the human T cells activation in situ, in response to the antigen recognition." (PMID 40944718, 2025). "Immunoblotting of isolated T cells revealed that α-LA directly promotes the expression of granzyme B, and the increased granzyme B expression in treated tumor tissues may, in part, be attributed to the accumulation of α-LA." (PMID 40595481, 2025). "Treatment with anti‐CD3/CD28 increased the frequency of CD137+/CD8+ T cells and induced cytokine responses dominated by IFNγ, IL‐2, and Granzyme B. While both non‐tumor and tumor‐border tissue responded to anti‐CD3/CD28, the intensities of immune responses were highly varied." (PMID 40952312, 2025). "In addition, the combination treatment group had a lower proportion of tumor‐infiltrating CD8+ Tex cells and higher proportion of IFN‐γ+GzmB+ T cells in the tumor site than the anti‐PD‐1 therapy group." (PMID 40013761, 2025).